AFP (alpha fetoprotein)
Diseases named in the same sentence as AFP in open-access papers (continued):
Sharing a sentence is not in itself a finding about the gene and the disease.
Down syndrome (40 papers, 2007 to 2025). "Abnormally low AFP values (most often a median value of <0.5) are associated with Down syndrome and other chromosomal abnormalities." (PMID 34746648, 2021). "Among 3 fetuses with abnormal quadruple test results, the risk factors of Down syndrome were 1/33 and 1/24 in 2 fetuses, and alpha-fetoprotein level was higher than normal range in third one." (PMID 26568762, 2015). "As with Down syndrome the pre-test risk increases with maternal age and the average marker profile is similar to Down syndrome for AFP, more extreme for NT, PAPP-A and uE3, and in the reverse direction for hCG, free β-hCG and inhibin." (PMID 26237388, 2014). "In the second trimester of pregnancy matemal serum α-fetoprotein (AFP) levels are, on average, lower in pregnancies associated with fetal Down syndrome than in unaffected pregnancies, and some centers offer antenatal screening for Down syndrome based on serum AFP as well as maternal ag e." (PMID 32503639, 2020). "Abnormally high levels of AFP in the maternal serum indicates elevated risk for neural tube defects of the fetus such as spina bifida or anencephaly, whereas abnormally low levels indicates elevated risk for a Down’s syndrome." (PMID 19690639, 2007). "Routine screening measures include first-trimester Down syndrome serological screening, mid-trimester maternal serum alpha-fetoprotein (AFP) testing, and systematic ultrasound examinations." (PMID 40997126, 2025). "The second screening test for Down syndrome was performed at the gestational age of 14 wk and 1 day to 20 wk by measuring 4 blood biomarkers (quad markers) including βhCG, uE3, inhibin A, and AFP." (PMID 40567908, 2025). "Regarding the biochemical markers of the second-round screening of Down syndrome, an increase in inhibin A and a decrease in AFP and UE3 are evident in some studies." (PMID 40567908, 2025). "Among the eight patients with AFP levels exceeding 1,000 ng/ml in the CSF and/or serum, only one, a patient with Down syndrome, succumbed to disease progression." (PMID 38500657, 2024). "The other patient, who had Down Syndrome and ventricular dissemination, presented with elevated CSF and serum AFP levels (>10,000 ng/mL)." (PMID 38500657, 2024). "An example of such evidence constitutes the development of maternal AFP screening for neural defects and amniocentesis for prenatal diagnosis of spina bifida and Down’s syndrome in the UK." (PMID 33128164, 2021). "During the study period of our project of prenatal screening for fetal Down syndrome, 13,406 women underwent quad test (AFP, b-hCG, uE3 and IHA)." (PMID 33059628, 2020). "It is able to detect 82–87% of fetuses with Down syndrome, The second trimester quadruple screening measures maternal serum markers (free β-hCG, AFP, uE3, and inhibin A) and detects 60–83% of fetuses with Down syndrome." (PMID 32664895, 2020). "AFP is associated with fetal defects and malformations, and abnormal levels of AFP in maternal serum have been used as an indicator of spina bifida or Down’s syndrome in fetal screening." (PMID 33009373, 2020). "The quad test or quadruple test is the most commonly used serum screening test for fetal Down syndrome, consisting of alpha-fetoprotein (AFP), human chorionic gonadotrophin (hCG), unconjugated estriol (uE3) and inhibin-A." (PMID 30971214, 2019). "There was significant difference in the MoM value for AFP between Down’s syndrome (aged 35–39 years) and NTDs (three age groups) compared with unaffected pregnancies." (PMID 31897392, 2019). "The SD of AFP log10(MoM) values was 0.1838 and 0.1784 in Down syndrome and unaffected pregnancies, respectively." (PMID 25846256, 2015). "Our data show that inclusion of AFP into the first trimester Down syndrome screening process improves screening performance." (PMID 25846256, 2015). "In Down syndrome, the correlation of AFP with free beta hCG and PAPP-A was 0.24864 and −0.06557, respectively." (PMID 25846256, 2015).
Down syndrome (continued). "As with AFP for NTDs, multi-marker screening tests for Down syndrome are less effective in twins than singletons." (PMID 26237388, 2014). "The present study used samples from Down syndrome screening, a double test combining total hCG and α-fetoprotein (AFP) measurements, which is offered to pregnant women in France during the second trimester of pregnancy." (PMID 25064170, 2014). "When multi-marker Down syndrome screening began the focus was in the second trimester using: hCG or free β-hCG and AFP (“Double” test); plus uE3 (“Triple” test); or both uE3 and inhibin A (“Quad” test)." (PMID 26237388, 2014). "Screening for NTD is now a routine prenatal test, mainly due to its association with second-trimester maternal serum screening for Down syndrome determined by combination of low AFP value and high hCG value." (PMID 25054433, 2014). "In the mid-1980s, when AFP was first shown to be a Down syndrome marker, it was thought to only be of use in screening young women, since older women were already regarded as at high enough risk to justify amniocentesis." (PMID 26237388, 2014). "Two patients with metastatic disease, one with Down Syndrome and AFP > 1,000ng/ml and the other with choriocarcinoma and pulmonary metastases, developed progressive disease resulting in death, as well as two other patients without evidence of disease, due to endocrinological disorders." (PMID 38500657, 2024). "AFP is high in fetal blood and increases in neural tube defects but decreases in Down syndrome." (PMID 36846633, 2023). "The identification of low maternal serum alpha-fetoprotein levels as a marker in Down syndrome led to quest and recognition of many serum markers and maternal serum markers of AFP uE3 and hCG were used in combination as triple test and with addition of Inhibin as the quadruple test." (PMID 24940359, 2014). "Abnormal levels of embryonic AFP are indicative of spina bifida or Down's syndrome in the fetus." (PMID 24922551, 2014). "In addition to structural imaging, several serum markers (hCG, PAPP-A, estriol, and AFP) can identify neurodevelopmental disorders such as Down’s syndrome and neural damage." (PMID 26085845, 2014). "Second trimester serum screening for Down's syndrome is routinely offered to women in the United Kingdom and United States, either with the triple test (alpha-fetoprotein (AFP), human chorionic gonadotrophin (HCG) and unconjugated estriol) or with the addition of inhibin A as the quadruple test." (PMID 18680570, 2008). "Measurements of the AFP levels in the maternal serum are undertaken at 14–22 weeks of each pregnancy and are part, along with unconjugated estradiol, human chorionic gonadotropin and inhibin A, of the quadruple test for antenatal Down’s syndrome screening." (PMID 19690639, 2007). "The most widely used markers of Down syndrome are maternal serum human chorionic gonadotrophin (hCG), the free-β subunit of hCG, pregnancy associated plasma protein (PAPP)-A, unconjugated estriol (uE3), inhibin A and AFP, and ultrasound nuchal translucency (NT)." (PMID 26237388, 2014). "This study demonstrated that among routinely measured biochemical markers for prenatal Down syndrome screening, serum uE3 exhibited higher predictive performance for AFGO than fβ‐hCG and AFP." (PMID 41034923, 2025). "Noninvasive examination of maternal serum alpha-fetoprotein (AFP) and free β subunit of human chorionic gonadotropin (free β-hCG) have been extensively applied in the detection of fetal Down’s syndrome (DS), open neural tube defects, Edwards’ syndrome, and other diseases." (PMID 33653375, 2021). "Maternal serum alpha-fetoprotein (MSAFP) concentration typically increases during pregnancy and is routinely measured during the second trimester as a part of screening for fetal neural tube defects and Down syndrome." (PMID 34746648, 2021).
Down syndrome (continued). "Taken alpha-fetoprotein (AFP) as an example, it is a well-known biomarker for a variety of problems of pregnancy, such as open neural tube defects, abdominal wall defects and Down’s syndrome." (PMID 34686127, 2021). "Unexplained high levels of alpha-fetoprotein (AFP) and inhibin A during antenatal screening can be confused with indications of neural tube defects or Down’s syndrome and may also be the first signs of the presence of adnexal masses." (PMID 33339178, 2020).
embryonal carcinoma (40 papers, 2009 to 2025). A non-seminomatous malignant germ cell tumor characterized by the presence of large germ cells with abundant cytoplasm resembling epithelial cells, geographic necrosis, high mitotic activity, and pseudoglandular and pseudopapillary structures formation. "The two cases of embryonal carcinoma seen in this study were associated with raised alpha-fetoprotein (AFP) and serum lactate dehydrogenase (LDH) levels." (PMID 38389620, 2024). "The risk for micrometastasis is higher with both embryonal carcinoma and a high level of AFP." (PMID 38817519, 2024). "The elevation of AFP is invovled in several physiological and pathological conditions, including hepatocyte regeneration, hepatocarcinogenesis, and embryonic carcinomas." (PMID 40575170, 2025). "In light of the AFP-positive embryonal carcinoma-like component obtained during the initial biopsy, we decided to treat the patient as intermediate risk." (PMID 38668041, 2024). "AFP is a glycoprotein normally produced by the yolk sac of the fetus, derived from the yolk sac or embryonic carcinoma component of germ cell carcinomas." (PMID 36016622, 2022). "Only one mixed germ cell NGC tumor with dysgerminoma and embryonal carcinoma exhibited elevated AFP." (PMID 33208175, 2020). "AFP elevation can also be seen in other histological subtypes of GCTs, such as IT and embryonal carcinoma, usually from hundreds up to thousands." (PMID 31836006, 2019). "On the other hand, AFP is only rarely positive in scattered embryonal carcinoma cells and helps in distinguishing yolk sac areas." (PMID 26137335, 2015). "In men with NSGCTs, AFP is produced by yolk sac (endodermal sinus) tumors and, less often, embryonal carcinomas." (PMID 27785191, 2012). "Embryonal carcinoma is capable of producing both AFP and HCG." (PMID 38817519, 2024). "In contrast, AFP is positive in only a few scattered cells, at most, in embryonal carcinoma." (PMID 27785191, 2012). "Malignant GCTs secrete alpha-fetoprotein (AFP), beta human chorionic gonadotropin (β-HCG), and embryonal carcinoma components." (PMID 40182369, 2025). "The results of this study show that the increase of AFP and HCG values have certain value in the diagnosis of embryonal carcinoma and mixed germ cell tumors." (PMID 36550425, 2022). "Contrary to the embryonal carcinoma cells, these cells forming gland-like spaces expressed GPC3 and AFP and showed stronger reactivity for pooled cytokeratins than the embryonal carcinoma component." (PMID 26880963, 2016). "Increased levels of AFP are typically found in non-seminomatous tumors (embryonal carcinoma and yolk sac)." (PMID 20535291, 2010).
cholangiocarcinoma (37 papers, 2010 to 2026). A carcinoma that arises from the intrahepatic biliary tree (intrahepatic cholangiocarcinoma) or from the junction, or adjacent to the junction, of the right and left hepatic ducts (hilar cholangiocarcinoma). "Because AFP can be elevated in patients with cholangiocarcinoma or metastatic colon cancer, its diagnostic use is less specific and beneficial." (PMID 39735678, 2025). "HCC and cholangiocarcinoma are associated with the elevation of alpha-fetoprotein (AFP) and carbohydrate antigen 19-9 (CA 19-9), respectively." (PMID 25880743, 2015). "An increased level of AFP is generally recognized as one of the markers for HCC development, while CA19-9 is more associated with cholangiocarcinoma." (PMID 41464759, 2025). "In the cholangiocarcinoma case, carbohydrate antigen 19-9 and alpha-fetoprotein levels helped to diagnose cholangiocarcinoma." (PMID 35078521, 2022). "To further identify the type of the tumors, we selected one marker for HCC (AFP) and another marker for cholangiocarcinoma (CK-19) to stain tissue sections from the same tumors." (PMID 22558209, 2012). "In the veterinary field, little is known about markers of HCC or cholangiocarcinoma with only a few prognostic markers, such as alpha-feto protein (AFP), investigated." (PMID 20167095, 2010). "Cholangiocarcinoma profiling was ordered along with alpha-fetoprotein (AFP)." (PMID 39347330, 2024). "The histological AFP score was a strong predictor (SHR 6.85, 95%CI (3.69–12.71), p = 0.001), as was the cholangiocarcinoma component (SHR 6.98, 95%CI (3.46–14.10), p < 0.001)." (PMID 34069594, 2021). "Recent studies also reported a case of AFP-producing ICC (serum AFP level: 1,560 ng/mL) expressing stem cell markers (CK14 and CD133) and AFP-producing cells in cholangiocarcinoma possessing cancer stem cell-like traits." (PMID 27301956, 2016). "Most ICC patients are in advanced stage when they are diagnosed due to the lack of specific early symptoms of cholangiocarcinoma and negative AFP." (PMID 34979994, 2022). "CEA, CA-19-9, and AFP testing were negative, therefore, the likelihood of this being adenocarcinoma of the pancreas or cholangiocarcinoma was low." (PMID 31667029, 2019). "Moreover, the early diagnosis efficiency of AFP was only 9–32%, and cholangiocarcinoma did not express AFP, which limited the clinical use thereof." (PMID 35854221, 2022). "Assuming that a small lesion has been seen on ultrasound, either in association with an elevated AFP or not, if the liver is cirrhotic this is highly likely to be HCC or a related cancer such as cholangiocarcinoma, or one of the mixed hepatocellular/cholangiocellular carcinomas." (PMID 36352896, 2022). "Further AFP and CK19 staining indicated that the PDX tumor and the original patient tumor were cholangiocarcinoma, not hepatic cell carcinoma." (PMID 37669935, 2023).
germinoma (37 papers, 2012 to 2025). A malignant germ cell tumor arising in the central nervous system. "Three of these cases had elevated HCG with germinoma histology, while four of these cases had elevated AFP—only one of which demonstrated ImT on histology (IMT)." (PMID 35205726, 2022). "Twenty-six had markers elevated above the SIOP CNS GCT 96 cut-off values, with the nongerminomatous diagnosis confirmed by surgery, except for a single case with a germinoma at biopsy and AFP of 30 ng/mL in CSF." (PMID 35884617, 2022). "The other patient with NGGCT (high AFP) had a local recurrence seven years after CSI RT with a histologically confirmed germinoma." (PMID 32937871, 2020). "All patients with a histologic diagnosis of germinoma, but one, had low CSF AFP level of less than 2.0 ng/ml." (PMID 32868820, 2020). "One patient’s pathology report indicated germinoma (case #16), but his AFP levels in CSF and serum were 6.4 ng/ml and 536.9 ng/ml, respectively." (PMID 32868820, 2020). "The immunohistochemical markers in current use include CD117/KIT, POU5F1 (OCT3/4), PLAP, and CT45 (germinoma); AFP, SALL4 and glypican 3 [yolk sac tumour (YST)]; CD30 (embryonal carcinoma); and HCG (choriocarcinoma)." (PMID 23861728, 2013). "β-HCG and AFP values in the serum and CSF of patients with pure germinoma." (PMID 38665953, 2024). "AFP tends to be negative in serum and CSF and has subordinate significance in the diagnostic of germinomas." (PMID 37036624, 2023). "All six ImT cases and 3-of-5 ImT cases with a germinoma component (60%) showed elevated AFP." (PMID 36995447, 2023). "The only case that demonstrated isolated CSF AFP elevation was germinoma with MT." (PMID 36995447, 2023). "Cases with a germinoma component showed lower AFP level (p = 0.046)." (PMID 36995447, 2023). "Elevated AFP was only observed in one germinoma case (serum AFP 85 ng/mL), a 4 year-old boy with pineal germinoma, treated with whole-ventricular irradiation and chemotherapy combining cisplatin and etoposide, who had no recurrence during 196 months of follow-up." (PMID 35205726, 2022). "In addition, germinoma is a common intracranial tumor of children, in which the AFP and β-hCG levels are generally significantly high." (PMID 35359354, 2022). "Seven patients with elevated β-HCG and normal AFP were clinically diagnosed as germinomas." (PMID 34858336, 2021). "Recently, the quantification of hCG and AFP in other biological fluids has gained great attention to support the diagnosis, prognosis and follow-up of neoplastic diseases deriving from trophoblastic cells, such as germinomas." (PMID 34829327, 2021). "To establish an appropriate cutoff value of serum β-HCG for diagnosis of intracranial germinomas, we retrospectively reviewed the records of intracranial tumor patients who received serum β-HCG and α-fetoprotein (AFP) tests for diagnostic purposes at our hospital from 2005 to 2014." (PMID 26771195, 2016). "Eight patients were diagnosed and treated based on CSF tumor marker elevation; four germinomas (BHCG 11.32–29.41 mUI/mL) and four NGGCT (BHCG 84.43–201.97 mUI/mL or positive AFP > 10 UI/mL)." (PMID 39035740, 2024). "The SIOP study defined germinoma with βHCG < 50 IU/L and NGGCT with serum or CSF AFP level of 25 ng/mL or higher and/or βHCG ≥ 50 IU/L." (PMID 39035740, 2024). "In a study in Brazil, cutoff levels for germinoma were undetectable levels of AFP and βHCG ≤ 200 mIU/L; NGGCT was defined as serum βHCG > 200 mIU/L and AFP > 5–10 ng/dL." (PMID 39035740, 2024). "The presence of bifocal lesions in the setting AFP and HCG within normal value is considered to be pathognomonic of germinoma and the trials in North America (ACNS 1123) and Europe (SIOP CNS GCT II) included patients without necessity of biopsy." (PMID 37860194, 2023). "They concluded that in the case of suprasellar and pineal region tumors with normal values for the tumor markers, β-hCG and AFP, in serum and elevated PLAP in CSF, the only possible diagnosis is a germinoma." (PMID 37697216, 2023).